IL10 (interleukin 10)
Diseases named in the same sentence as IL10 in open-access papers (continued):
Sharing a sentence is not in itself a finding about the gene and the disease.
infection (continued). "An infection localized to the pancreas would be unlikely to induce such expression, but it has been hypothesized that infected islet cells can secrete IL-10 to avoid extensive T cell recruitment." (PMID 34489972, 2021). "During acute secondary infection with heterologous DENV, highly cross-reactive CD8+ T cells with high avidity are preferentially activated, which produce high levels of pro- and anti-inflammatory cytokines such as TNF-α, IFN-Υ and IL-13, but lower levels of IL-10." (PMID 33231723, 2021). "For example, infection-induced levels of TNF-α, IL-1β, and IL-17A were higher in the sera of pregnant mice than in the sera of virgin control mice, which parallels their increased bacterial burden, whereas the anti-inflammatory cytokine IL-10 peaked to higher levels in virgin than in pregnant mice." (PMID 33622714, 2021). "After the infection with A. hydrophila, AKG supplementation significantly increased the gene expression level of IL-10, which indicated that AKG could inhibit the overexpression of pro-inflammatory factors, and enable the fish to remain in a steady state under inflammatory response conditions." (PMID 34220849, 2021). "Cytokines were also involved in the immune responses to IAVs infections, and substantial increases in IL-6 cytokine levels were observed on 2 days after infection and gradually decreased over the course of infection, IFN-γ and IL-10 levels increased on 6 or 7 days after infection." (PMID 34060982, 2021). "IL-10GFP+ NK cells were also the main population in the spleen, blood, and brain of untreated mice but only until day 6 post-infection, when there was death from ECM, suggesting that IL-15C treatment induces early IL-10 production that may be related to the protective effect." (PMID 35053151, 2021). "CXCL9 was not assessed by these studies and, together with IL-10, might represent a potential biomarker to detect asymptomatic infections." (PMID 33407502, 2021). "However, the IL-10 expression was increased after treatment with only NF-κB inhibitor in Ms_Rv0580c infected THP-1 cells, as compared to Ms_pNIT infected THP-1 cells, at 24 h post-infection." (PMID 33535567, 2021). "Previous experimental vaccine trials have also suggested that IL-10 might help control the first steps of viral replication and mitigate the damaging costs of an intensified inflammatory response that is characteristic of acute ASFV infections." (PMID 34203976, 2021). "(C) The level of IL-12/23 p40 and IL-10 didn’t change with the change of intracellular CFU (P<0.05), while the level of TNF-α and IL-6 increased with the intracellular CFU decreasing, and the increase level of TNF-α was lower than that of the infection group (P<0.05)." (PMID 35003120, 2021). "Though CB3-infected MDA5+/- mice have similar levels of inflammatory cytokines TNF-α, IFN-γ, IL-6, IL-17a, and IL-10 (data not shown) by day 7 following infection, CB3-infect MDA5+/- mice have greater systemic levels of both IFN-α and IFN-β compared to CB3-infected wt mice." (PMID 34804036, 2021). "Interestingly, expression of pro-inflammatory IL-1 was modestly down-regulated in all cell types after infection, whereas IL-10 and TNFα expressions were not significantly regulated by infection in this system." (PMID 33730024, 2021). "Importantly, evidence suggests that IL-10 production by NK cells is induced during disseminated, but not during locally restricted, infections." (PMID 35053151, 2021). "Infection can stimulate the expression of pro-inflammatory genes, such as IL-6, TNF-α, etc., which can effectively eliminate microorganisms, accelerate tissue repair, and secret IL-10 and other anti-inflammatory cytokines to alleviate the inflammatory reaction." (PMID 33868293, 2021). "Indeed, L. monocytogenes stimulated IL-10 production by mouse splenic, liver, and pbNK cells at 72 and 96 h post infection, but not at 24 h, which coincides with the peak of IFN-ɣ production by NK cells." (PMID 33903735, 2021).
infection (continued). "The levels of IL-2, IL-4, IL10, and IL-17 were also not significantly altered by infection." (PMID 33815321, 2021). "In our experiments, we did not observe secretion of IL-10 from Breg B cells after infection." (PMID 34209841, 2021). "Similarly, the evolution of the infection process in dogs may be determined correlating the parasite load with the TNF-α and IL-10 level in the spleen." (PMID 32983013, 2020). "In our experiment, cytokine values, especially IFN-γ, IL-10, and IL-21, were not particularly high, which may be related to the low number of cercariae infection." (PMID 33330140, 2020). "Therefore, the presence of IL-10 soon after transmission may trigger DC-mediated IRs that help HIV survival and infection." (PMID 31978062, 2020). "Conversely, we observed that infection of murine macrophages showed a significant increased secretion of only two pro-inflammatory cytokines (IL-12p70, and TNF) and one anti-inflammatory cytokine (IL-10) in infected RAW264.7 cells, with similarly low levels of these cytokines in mock-infected cells." (PMID 32163514, 2020). "Moreover, in the absence of IL-6, IL-10 secretion was slightly enhanced only upon infection with lower bacterial loads while IL-6 KO macrophages stimulated with LPS showed no alterations in IL-10 secretion when compared to wild-type cells." (PMID 33322581, 2020). "Interestingly, in infected cultures IL-6 and TNFα levels did not increase on day two while for IL-10 the upward trend was maintained at this time point and throughout the three days after infection with MCMV." (PMID 32455939, 2020). "Some reports have indicated that the infection with hMPV provokes low levels of IL-10, and that the low secretion of IL-10 might play a negative role in the severity of hMPV-infection within preterm infants." (PMID 32545470, 2020). "On the 4th day after infection, when an accumulation of pulmonary dendritic cells in the lymph nodes was observed (necessary for the CD8+ T-cell response), it was noted that IFNLR1 knockout leads to upregulation of the LOC101055769, RGS9BP, TMEM246, WRD31, and IL10 genes." (PMID 33255985, 2020). "On the other hand, infection with T. cruzi in the absence of IL-10 promotes the upregulation of these M2 markers that could not be further increased by fenofibrate." (PMID 33072115, 2020). "However, upon the tail vein injection of HA‐HuR expression plasmid in infected animals, the expression levels of cytokines IL‐10 dropped while the TNF‐α expression had increased in liver, and interestingly, infection levels measured by Ld kinetoplastid DNA content dropped in mouse liver." (PMID 32031337, 2020). "However, detailed preclinical and clinical studies investigating the association between serum IL-10 levels and post-SAH infections are still lacking." (PMID 32106601, 2020). "The levels of IL-10 and TGF-β were dramatically increased upon the treatment of rSj-Cys in this study, indicating that rSj-Cys acted as an inhibitory immunomodulator in the case of excessive inflammation infection possibly through stimulating Treg and Treg cell-secreted IL-10 and TGF-β." (PMID 32423469, 2020). "The only difference between the two routes of administration was the IL-10 secretion by splenocytes of ID immunized sheep (not seen in IN sheep), suggesting that IL-10 could participate in favoring infection." (PMID 33013917, 2020). "In absence of infection, nicotine acted as an immunosuppressive drug, increasing M2 macrophages and IL-10 cytokine; however, upon MAP infection, the anti-inflammatory role of nicotine was lost to a robust pro-inflammatory response even higher than that observed with infection only." (PMID 32370298, 2020). "The NF-κB downstream signaling induced the IL-10 and GBP-1 might be inhibited the activation of caspase-3 and leads to attenuate the macrophages apoptosis, thereby fostering its intracellular survival of mycobacteria and establishment of infection." (PMID 32117813, 2020).
infection (continued). "However, in BMDMs the increased induction of IL-10 driven by the Δmmpl7 mutant Mtb over WT Erdman was recapitulated by addition of DATs to WT Erdman infection, thus suggesting that DAT overexpression on Δmmpl7 mutant Mtb actively induced expression of anti-inflammatory IL-10 produced by macrophages." (PMID 32695111, 2020). "Even so, increased secretion of IL-10 upon infection has been reported, which could explain the lack of response described for this virus, as this cytokine will induce a state of tolerance in the surveilling immune cells." (PMID 32765522, 2020). "Only TLR2-/-TLR5-/-Unc93b13d/3d mice failed to express significant IL-10 after Δhly infection." (PMID 32634175, 2020). "Moreover, the increase in T reg, observed during convalescence, is not accompanied by IL-10 elevation, suggesting that these cells are not the source of serum IL-10 in the late phases of the infection." (PMID 33066100, 2020). "To determine whether fenofibrate could exert the same effect in the absence of IL-10 in the single infection model, we assessed the levels of mRNA expression of the M1 markers IL-6, TNF-α and NOS2 in knock out mice." (PMID 33072115, 2020). "No significant secretion of IL-4 and IL-10 was observed in any experimental group before infection." (PMID 32526867, 2020). "TLR agonists induced low IL‐10 cytokine production which did not change following infection." (PMID 32566226, 2020). "However, IL-10 blockade resulted in increased hippocampal damage during acute infection, which is usually only minimal or absent in SJL mice." (PMID 32131483, 2020). "While all CD14+CD16+(classical monocytes), CD14dimCD16+ (intermediate) and CD14−CD16++(non-classical) monocytes are susceptible to infection by the DENV, the non-classical monocytes are the main produced of inflammatory cytokines and IL-10, which are implicated in SD." (PMID 33194836, 2020). "Similarly, in E. tenella infection IL-10 mRNA was upregulated in the caeca post-infection, although there does not appear to be a clear relationship between IL-10 expression during infection and caecal pathology." (PMID 32175341, 2020). "While infection with Δhly induced significant IL-10 secretion from WT BMMs, Δhly induced almost no detectable IL-10 secretion in TLR2-/- BMMs, suggesting that bacterial lipoproteins are the major activators of IL-10 secretion in response to infection with Δhly." (PMID 32634175, 2020). "However, the combination of simvastatin with DAPT produced a trend toward increasing levels of TNF-α and IL-1β without affecting IL-10 although these cytokines never reached the levels observed with the infection." (PMID 32393497, 2020). "In this study, despite differing between the febrile phase and convalescence, the levels of IL-10 were within the normal range during adenoviral AURTIs, suggesting that, in these infections, this cytokine does not play a significant role in modulating systemic inflammation." (PMID 33066100, 2020). "Furthermore, the levels of interleukin (IL)-2, IL-4, IL-6, IL-22, and interferon (IFN)-γ, but not that of tumor necrosis factor alpha (TNF-α), IL-10, and IL-9, increased to their highest levels at day 4 post-infection and decreased thereafter." (PMID 31711531, 2019). "Moreover, IL-6, IL-10, TNF-α and IFN-γ mRNA were found to be significantly increased in the trigeminal ganglia (TG) of 2-week-old piglets infected with virulent PRV strain NIA3 at 2 days post-infection." (PMID 31675371, 2019). "Interestingly, IL-10-producing-tolerogenic DCs were observed after infection with live MAH, rather than with inactivated or dead MAH." (PMID 31440223, 2019). "However, the production of IL1B was not affected by IL10 knock-down during AF2122/97 infection at the mRNA or protein level." (PMID 31527895, 2019). "However, NOS2 mRNA levels were not significantly affected during AF2122/97 infection by the absence of IL10." (PMID 31527895, 2019).
infection (continued). "The mean inclusion size for CA mφ without IL-10 was 0.0088 arbitrary units with a standard deviation of 0.0058 and 0.0037 arbitrary units with a standard deviation of 0.0034 for treatment at time of infection." (PMID 31134002, 2019). "Furthermore, cytokine (IFN-γ and IL-10) production during infection was also attributed to CD4+ but not CD8+ T cells." (PMID 31824512, 2019). "Maternal infection during pregnancy was associated with a 7% lower CRP level (among offspring compared with offspring born to women without an infection (95% CI, − 17,5%) and similarly an 8% lower level of IL-6 (95% CI, − 15, 1%), and a 9% lower level of IL-10 (95% CI, − 23,20%)." (PMID 30923624, 2019). "Moreover, microarray assay in combination with CRNG interference and overexpression showed that the differential genes such as ANPEP, KITLG, STAT5A, FOXP3, miR-451, IL-2, IL-10, IL-6, and TNF-α are mainly involved in viral and pathogens infection and the immune-inflammatory responses in PK-15 cells." (PMID 31178726, 2019). "Moreover, silence of the thymine DNA glycosylase (TDG), a Rep-binding protein, significantly reduced the binding activities of NF-κB p50 and Sp1 with il10 promoter, resulting in the reduction of IL-10 production in PCV2-inoculated PAMs at the later phase of infection." (PMID 31835539, 2019). "In fact, as the severe infection grew unabated, the body entered a state of excessive inflammation that the anti-inflammatory response (IL-10) could not balance." (PMID 31681022, 2019). "Remarkably, at the end of week 8 after infection, Th1 responses were observed in the saline treated, as well as in the F1 and F3-vaccinated mice that exhibited increased IFN-γ/IL-10 ratios, and in the saline treated and F1-vaccinated mice, that showed elevated TNF-α/IL10 ratios." (PMID 31024556, 2019). "However, CD4+ T cell depletion decreased production of IL-2 and IL-10 in early stage infection, decreased production of IL-17 and TNF-α, and abolished IL-3 production in both early and late stage infection." (PMID 31608052, 2019). "However, IL-12/STAT4 signaling is not required for NK cell IL-10 secretion in the context of Listeria monocytogenes (Lm) bacteria or murine cytomegalovirus (MCMV) infections." (PMID 31552035, 2019). "Furthermore, it was shown that the modified Th2 responses in MF+ individuals are accompanied with higher frequencies of Treg and alternatively activated macrophages as well as increased secretion of IL-10, TGF-β and infection-specific IgG4: all promoting parasite survival." (PMID 31120872, 2019). "Although GM-CSF and IL-2 were expressed in higher concentrations at 6 h post-infection in ESRD group, the production of a large number of pro- and anti-inflammatory cytokines as well as chemokines, including IL-8, IL-12p40, TNF-α, MCP-1, MIP-1b, and IL-10 was markedly decreased." (PMID 31875015, 2019). "Moreover, whereas the infection of SFTSV possessing wild-type NSs was lethal in IFNAR−/− mice, recombinant SFTSV possessing NSs-P102A rescued 70% of mice, suggesting IL-10 expression might be a key factor that contributes to the pathogenesis of SFTSV." (PMID 31547199, 2019). "The results showed that only the silencing of TDG could significantly decrease the production of IL-10 at 48 h post rAd-Rep2 infection, while the silencing of other Rep-binding proteins did not significantly affect IL-10 production in rAd-Rep2-infected PAMs." (PMID 31835539, 2019). "Of note, infection with the USA300 WT led to a significantly enhanced production of IL-10 at 6 to 24 h pi in the spleen, but the infection with the S. aureus Δαβδ mutant strain did not induce IL-10 secretion, indicating a PSM-dependent anti-inflammatory response." (PMID 31134074, 2019).
infection (continued). "Severe IV infection induces many cytokines; IFNαβ, TNFα, IFNγ, C-X-C motif chemokine (CXCL) 10 (CXCL10), CXCL9, C-C motif ligand (CCL) 2 (CCL2), CCL4, CCL5 and interleukin (IL)−6 (IL-6), IL-2, IL-8, and IL-10 have all be observed to be upregulated during severe IV infection in humans." (PMID 30250466, 2018). "Expression of an array of cytokines (CSF3 [G-CSF], IFNγ, IL-1β, IL-6, IL-22, IL-17A, and IL-10), chemokines (CCL20, CXCL2 and CXCL9) and receptors (CD40) known to be involved in the regulation of S. pneumoniae inflammatory response was measured at 0, 6, 24, and 48 h post-infection." (PMID 30333823, 2018). "At the 14th day post-infection, there was a decrease switch in the number of CD4+ IL-10+T+ cells observed in WT and ST2−/− mice with an increase in ST2−/− mice and it lined up with the IL-10 amounts in infected joints at all times points evaluated (7–28 days post-infection)." (PMID 29867945, 2018). "After 1, 3 and 7 d of post-infection (PI), the samples needed for detecting of the mRNA levels of mouse beta-defensin (mBD)-1, mBD2, mBD3, mBD4, mBD6, cathlin-related antimicrobial peptide (CRAMP), interleukin (IL)-10, IL-12 and parasite load were taken under standard methods." (PMID 30697304, 2018). "In addition, LJM19-immunized hamsters exhibited increased production of IFN-γ and IL-10 after exposure to uninfected sand fly bites, suggesting that this DTH response could be a marker of protection against infection by L. infantum." (PMID 30519235, 2018). "Naïve and nematode-infected GF mice display a reduction in RORγt+ Treg in the gut and gut-draining lymph nodes, while GATA-3+ Treg expanded similarly in SPF and GF mice and formed the major IL-10 producing Treg subset upon infection irrespective of the microbial status." (PMID 30349532, 2018). "Similar to infections caused by non-MDR bacteria, the production of IL-10 may lead to a better or worse outcome depending of the infecting bacteria." (PMID 30279680, 2018). "Twenty-four hours after infection, we assessed inflammatory responses of the macrophages by measuring the levels of cytokines, including granulocyte/macrophage colony-stimulating factor (GM-CSF), IFN-γ, interleukin (IL)-2, IL-4, IL-6, IL-8, IL-10 and TNF-α, secreted in the culture supernatant." (PMID 29712918, 2018). "Examination of the gingivae for pro and anti-inflammatory cytokine expression 4 days post infection revealed that treatment with RvD2 maintained tissue homeostasis by preventing increased expression of the pro-inflammatory cytokines, such as IFN-γ, IL-1β, and TNF-α and decreased expression of IL-10." (PMID 29922275, 2018). "We have previously established 10-weeks post-infection as a key time-point in immunomodulation where SEA (schistosome egg antigen) specific B cells are recruited to the liver, and immune-complex ligation of hepatic macrophages begins, leading to macrophage IL-10 production." (PMID 30483256, 2018). "Infection with EV 71 can activate the c-Jun NH2-terminal kinase (JNK) and p38 mitogen-activated protein kinase (MAPK) signaling pathways, thereby contributing to increased viral replication and secretion of cytokines such as interleukin (IL)-2, IL-6, IL-10, and tumor necrosis factor (TNF)-α." (PMID 30545363, 2018). "The gene expression of TNFα, IFNγ and IL-10 within ‘ATL-like’ cells was higher in patients with non-malignant infection compared to ATL (p = 0.048, p = 0.031 and = 0.056 respectively) in keeping with relative frequencies of cytokine secreting cells by intracellular cytokine staining." (PMID 29444188, 2018). "However, we have recently reported the role of IL-10 during an infection with non-MDR-Salmonella enterica serovar Typhimurium." (PMID 30279680, 2018). "However, the present data clearly indicate that IL-10-mediated responses - at least during the acute infection phase - do not account for insufficient antiviral immunity of SJL mice in the TME model." (PMID 29666403, 2018).